CSF1 (colony stimulating factor 1)
Diseases named in the same sentence as CSF1 in open-access papers (continued):
Sharing a sentence is not in itself a finding about the gene and the disease.
ovarian carcinoma (59 papers, 1995 to 2026). A malignant neoplasm originating from the surface ovarian epithelium. "In ovarian cancer, high levels of CSF-1 in the serum and ascites are associated with poorer patient outcomes." (PMID 35020853, 2022). "Overexpression of CSF1R or its ligand CSF1 is found in various solid tumors, including those associated with breast, prostate, and ovarian cancer, and plays an important role in tumor malignancy and metastasis." (PMID 33796453, 2021). "Elevated levels of CSF-1 promote progression of ovarian cancer, by binding to CSF-1R (the tyrosine kinase receptor encoded by c-fms proto-oncogene)." (PMID 22909061, 2012). "CSF-1 was also associated with cancer virulence by having the capacity to augment the invasive ability of human ovarian cancer cells, and by promoting metastasis." (PMID 22909061, 2012). "Moreover, increased expression of CSF-1 in breast and ovarian cancer cells has been associated with poor prognosis." (PMID 39687616, 2024). "Both the knockdown of CSF‐1 or reactivation of miR‐130b expression using the DNMT inhibitor 5‐aza‐CdR were shown to sensitize drug‐resistant ovarian cancer cells to anticancer drugs." (PMID 40968783, 2026). "The microenvironment of ovarian cancer tumors is rich in IL-6, IL-10, and CSF-1, which promotes M2 polarization and the accumulation of M2 macrophages." (PMID 39981173, 2025). "Then, CSF-1 activates its receptor CSF-1R to affect the survival, proliferation, migration and invasiveness of cancer cells like breast and ovarian cancer cells." (PMID 39687616, 2024). "ALKBH3 reduces m1A methylation, increases the stability of macrophage colony-stimulating factor (CSF-1) mRNA, and promotes the progression of breast and ovarian cancers." (PMID 39726589, 2024). "In ovarian cancer preclinical models, CSF-1/CSF-1-R blockade has only been investigated via small-molecule inhibitors as opposed to mAbs." (PMID 35020853, 2022). "The ALKBH3-dependent m1A demethylation of macrophage colony-stimulating factor 1 (CSF1) mRNA enhanced its mRNA stability and thus promoted the invasion of breast and ovarian cancer cells." (PMID 35627295, 2022). "Particularly, ALKBH3 can promote the invasion of breast and ovarian cancer cells by m1A demethylation of colony stimulating factor 1 (CSF-1) mRNA." (PMID 33430133, 2021). "RT-qPCR analyses showed that NHWD-870 treatment significantly decreased CSF1 mRNA in a panel of moue and human ovarian cancer and melanoma cell lines." (PMID 32286255, 2020). "GAPDH binding enhances CSF-1 mRNA stability, increasing CSF-1 expression, which is an indicator of poor prognosis in patients with ovarian cancer." (PMID 29991493, 2018). "Clinical specimens from ovarian cancer metastases display strong immunostaining for both CSF-1 and its receptor in contrast to noninvasive borderline tumors and to benign ovarian tissue." (PMID 25935153, 2015). "High levels of CSF-1 have also been shown to be a poor prognostic factor in ovarian cancer, when expressed in the tumor epithelium." (PMID 24936477, 2014). "miR-130b* has been reported to target colony-stimulating factor (CSF)-1 and to be involved in multidrug resistance in ovarian cancer and in papillary thyroid carcinoma development." (PMID 24914051, 2014). "CSF-1 is a cytokine considered to induce differentiation of macrophages to an M2 phenotype and is overexpressed in human ovarian cancers." (PMID 24936477, 2014). "In this report, we study 3’UTR targets for binding miRNAs, and find that both miR-128 and miR-152 down-regulate CSF-1 expression in ovarian cancer." (PMID 22909061, 2012). "This monomer is processed further by glycosylation and forms an over 200 kDa homodimeric glycoprotein which is the most abundant form of secreted CSF-1 in ovarian cancer." (PMID 22909061, 2012). "Our goal is to identify miRNAs that down-regulate CSF-1 expression, and eventually open an avenue for possible treatment options for ovarian carcinomas." (PMID 22909061, 2012).
ovarian carcinoma (continued). "This down-regulation of CSF-1 mRNA by both miRNAs is observed in the context of differing miRNA expression patterns in the ovarian cancer cells." (PMID 22909061, 2012). "Previously, we identified GAPDH protein which binds to ARE and stabilizes CSF-1 mRNA leading to post-transcriptional up-regulation of CSF-1 in ovarian cancer cells." (PMID 22909061, 2012). "It has been previously established that CSF-1 imparts invasiveness and metastasis in epithelial ovarian cancer." (PMID 22909061, 2012). "Colony stimulating factor-1 (CSF-1) plays an important role in ovarian cancer biology and as a prognostic factor in ovarian cancer." (PMID 22909061, 2012). "In ovarian cancer, CSF-1 also has an important role as a biomarker and prognostic factor, as high levels of this protein were linked to poor patient outcome." (PMID 22909061, 2012). "Despite this difference in baseline expression pattern, we find that both miRNAs down-regulated CSF-1 mRNA and protein in ovarian cancer cells." (PMID 22909061, 2012). "The current study identifies miR-128 and miR-152 as important regulators for CSF-1 mRNA and protein expression, and of ovarian cancer cell behavior." (PMID 22909061, 2012). "In this report, we investigate the effect of miRNAs on post-transcriptional regulation of CSF-1 mRNA in human ovarian cancer." (PMID 22909061, 2012). "We have also found that both miR-128 and miR-152 down-regulate CSF-1 mRNA and protein expression in ovarian cancer cells leading to decreased cell motility and adhesion in vitro, two major aspects of the metastatic potential of cancer cells." (PMID 22909061, 2012). "Our results provide the evidence for a mechanism by which miR-128 and miR-152 down-regulate CSF-1, an important regulator of ovarian cancer." (PMID 22909061, 2012). "In ovarian cancer cells, a major unprocessed CSF-1 of 60.1 kDa polypeptide is produced by the 3,939nt transcript." (PMID 22909061, 2012). "We have shown that this is due, at least in part, to CSF-1 regulation of uPA, a well-known marker of invasiveness in ovarian cancer." (PMID 22909061, 2012). "To correlate selected miRNA expression patterns with CSF-1 mRNA and protein expression, we used three ovarian cancer cell lines and NOSE.1 ovarian epithelial cells which are minimally invasive." (PMID 22909061, 2012). "Our findings demonstrate that both miR-128 and miR-152 can negatively impact cell motility and adhesiveness of human ovarian cancer cells, important aspects of their metastatic potential, correlated with suppression of CSF-1 expression." (PMID 22909061, 2012). "Colony‐stimulating factor (CSF‐1) is a direct downstream target of miR‐130b, as confirmed by dual‐luciferase reporter assays and further validated by qRT‐PCR, immunohistochemistry, and ELISA in ovarian cancer tissues and cell lines." (PMID 40968783, 2026). "For example, with CSF-2 (known as granulocyte-macrophage colony-stimulating factor, GM-CSF), knock-out mice show reduced neutrophil function, and CSF-1 (known as macrophage colony-stimulating factor, M-CSF) has been observed to increase the Th1/Th2 ratio in ovarian cancer patients." (PMID 38612319, 2024). "In addition, m1A modification regulates colony-stimulating factor 1 expression in breast and ovarian cancer cells, which indicates that m1A modification is responsible for regulating immune surveillance in cancer." (PMID 38118002, 2024). "However, in a syngeneic ovarian cancer mouse model, a combination of CSF-1 inhibition with chemotherapy docetaxel reduced tumour lung metastasis." (PMID 35020853, 2022). "In addition, we found that increased CSF1 expression was correlated with a worse outcome in ovarian cancer patients, as determined by a Kaplan–Meier survival curve." (PMID 35406623, 2022). "Furthermore, we test our model for CSF1 enhancer function in ovarian cancer cells and demonstrate that our findings can apply to other cancer types." (PMID 35406623, 2022).
ovarian carcinoma (continued). "In this context, elevated levels of CSF1 and expression of CSF1R have been associated with poor prognosis in different cancers such as breast and ovarian cancer and, consequently, different strategies have emerged to neutralize or inhibit the CSF1/CSF1R signaling in several cancers." (PMID 34298983, 2021). "Thus, downregulation of miR-130b promotes the development of multidrug resistant ovarian cancer partially by binding of miR-130b to its target mRNA of the colony-stimulating factor 1 (CSF-1)." (PMID 35582723, 2019). "Expression of CSF-1 is higher in malignant ovarian tumors compared to borderline and benign tumors." (PMID 24936477, 2014). "Down-regulation of GAPDH by siRNA decreases CSF-1 expression in ovarian cancer cells." (PMID 22909061, 2012). "In the present study, our goal was to identify miRNAs that down-regulate CSF-1 expression, a small step in our overall quest to find specific inhibitors which may ultimately impact on ovarian cancer metastasis." (PMID 22909061, 2012). "We predict that, since the 3,939nt CSF-1 transcript has a vast (2,172nt) 3’UTR, miRNAs may play an important regulatory role in mediating the cellular levels and biological functions of CSF-1 in ovarian cancer." (PMID 22909061, 2012). "Macrophage colony-stimulating factor 1 (CSF-1) concentration was also assayed as its serum level is increased in ovarian cancer and CSF-1 may be involved in the regulation of collagen metabolism." (PMID 9667653, 1998). "Furthermore, hypermethylation of miRNA-130b was found to be linked to ovarian cancer tumorigenesis and drug resistance, while miRNA-130b restoration sensitized ovarian cancer cells to taxol and CDDP, using colony-stimulating factor 1 (CSF1) as a direct target." (PMID 34944633, 2021). "GAPDH binds AU-rich elements in the 3′UTR of mRNA, an activity that is reported to have two possible outcomes; on the one hand, it may result in mRNA stabilisation, thus enabling translation, as is the case for GAPDH binding to colony stimulating factor 1 in ovarian cancer cells." (PMID 30659183, 2019). "While some differential effects of miRNA alteration are seen between the different ovarian cancer cell lines, overall, the effect of miR-128 and −152 on down-regulation of CSF-1 expression are similar, and may be achieved by both translational repression and mRNA decay." (PMID 22909061, 2012). "Together, our findings underscore the potential involvement of cellular pathways such as CSF1/CSF1R and AR in the development of epithelial ovarian cancer and the response to flutamide treatment." (PMID 39622842, 2024). "In a murine model of Bevacizumab-resistant ovarian cancer, tumours exhibited restored response when treated with a TAM-depleting anti-CSF-1 mAb." (PMID 35020853, 2022). "Colony-stimulating factor 1 (CSF1), a macrophage cytokine, is strongly correlated with poor prognosis in ovarian cancer patients." (PMID 36329701, 2022). "In breast and ovarian cancer, ALKBH3 functions as an oncogene for cancer invasiveness via stabilizing colony-stimulating factor 1 (CSF-1) transcript in an ALKBH3-mediated m1A demethylation manner." (PMID 34272618, 2021). "The low expression of miR-130b reduce the efficiency in binding to CSF-1 3’UTR, thereby reducing the sensitivity of ovarian cancer cells to cisplatin and paclitaxel." (PMID 25342041, 2014). "Expression of miR-128 is significantly inversely correlated with CSF-1 protein expression (correlation coefficient = −0.998, p = 0.002), with miR-128 RNA level low in Hey and SKOV3 and high in Bix3 ovarian cancer cells, as well as in NOSE.1 ovarian cells." (PMID 22909061, 2012). "While miR-128 and miR-152 possess target sequences in the CSF-1 mRNA 3’UTR, their expression patterns in the ovarian cancer cell lines proved to be different." (PMID 22909061, 2012).
ovarian carcinoma (continued). "Inhibitors of CSF1R or its ligand CSF1 interfere with tumor-promoting TAMs or other myeloid cells in the TME and are currently being tested in clinical trials for treatment of several types of malignancies, such as CRC, melanoma or ovarian cancer." (PMID 39425000, 2025). "In ovarian cancer, ALKBH3 can extend the half-life of CSF-1 mRNA and enhance the expression of CSF-1 by making CSF-1mRNA near the origin of translation 5’UTR region m1A demethylation, thereby improving the invasion ability of ovarian cancer cells." (PMID 38343637, 2024). "In breast and ovarian cancers, ALKBH3 induces the abundance of m1A-modified colony-stimulating factor 1 (CSF1) mRNA, which enhances its translation initiation and cancer cell invasiveness, while it can also promote cancer cell invasion through destabilization of tRNAs." (PMID 39459530, 2024). "Our present study bridges this knowledge gap by showing how these miRNAs modulate the expression of CSF1R and AR in ovarian cells, implicating their significant roles in regulating CSF1/CSF1R and AR signaling pathways during the development of epithelial ovarian cancer in HR women." (PMID 39622842, 2024). "Therefore, to test our model in ovarian cancer cells, we created dCas9-KRAB expressing OVCAR3 cell lines and repeated the CRISPRi experiments using the same sgRNAs to epigenetically repress the CSF1 enhancer." (PMID 35406623, 2022). "Moreover, E2F3, a downstream signaling molecule of CSF-1, has been found to increase expression of E2F3 in prostate cancer, ovarian cancer, and lung cancer, and the expression of E2F3 in TAMs can promote lung metastasis of tumors." (PMID 33224886, 2020). "Clinically used soluble markers for cancer diagnosis include mesothelin in malignant pleural mesothelioma, colony stimulating factor-1 (CSF-1) for endometrial carcinoma, prostate specific antigen (PSA) for prostate cancer, and carcinoembryonic antigen, CA125, for ovarian cancer." (PMID 31323992, 2019). "To ascertain if the enhancer was active in ovarian cancer cells and may be responsible for this increased expression, we downloaded publicly available H3K27ac and BRD4 ChIP-seq datasets and looked for the enrichment of these marks at the CSF1 enhancer region." (PMID 35406623, 2022). "Importantly, further studies have found that IL-34 is highly expressed in ovarian cancer cells and tissues, which is associated with poor progression-free survival (PFS) and overall survival, while the expression of CSF-1 has not changed." (PMID 33224886, 2020). "A relatively small number of ovarian cancer cell lines may not give sufficient information when comparing miRNA expression patterns to effect on target mRNA (CSF-1 mRNA)." (PMID 22909061, 2012). "Notably, an increasing amount of evidence has indicated that ovarian cancer cells can polarize TAMs toward the M2 phenotype by upregulating the expressions of leukemia inhibitory factor (LIF), IL-6, and colony stimulating factor-1 (CSF-1), in the intraperitoneal tumor microenvironment." (PMID 30568223, 2019).
melanoma (58 papers, 2006 to 2026). A malignant, usually aggressive tumor composed of atypical, neoplastic melanocytes. "CSF1 is a key regulator of the tumor microenvironment, promoting the differentiation and accumulation of immunosuppressive tumor-associated macrophages (TAMs) and correlating with disease progression and resistance to immune checkpoint blockade in melanoma." (PMID 40805206, 2025). "CSF1 (CSF1R ligand) expression of melanoma and NSCLC cells is associated with the MDSC enrichment, which could be inhibited via the blockage of CSF1/CSF1R in vitro." (PMID 32508809, 2020). "In human melanoma, the expression of CSF1 in blood was significantly higher in metastatic melanoma than in healthy subjects." (PMID 37097499, 2023). "CSF1 expression correlated with the abundance of CD8 T cells and CD163 tumor-associated macrophages (TAMs) in melanoma." (PMID 37097499, 2023). "By exploring pan-cancer TCGA dataset, we found that immunosuppressive cytokines, such as TGF-β, PGE-2 and CSF1, are highly expressed across all cancer types, including melanoma samples." (PMID 38239354, 2023). "Circulating CSF-1 levels in melanoma patients are significantly higher than in healthy donors and positively correlated with disease progression." (PMID 32793228, 2020). "Investigations of human melanoma cells show that IFN-γ produced by Th1 cells induces the expression of colony-stimulating factor 1 (CSF-1) and promotes tumor infiltration by M2-type TAMs." (PMID 33062717, 2020). "An interesting investigation was performed on the SM1 murine melanoma cell line, known to secrete high amounts of CSF-1, and induced to express the highly immunogenic protein ovalbumin (SM1-OVA)." (PMID 33212945, 2020). "Colony-stimulating factor 1 (CSF1/M-CSF) also contributes to resistance of melanoma to PD-1 blockade." (PMID 30191140, 2018). "Colony stimulating factor 1 (CSF-1) is one such cytokine secreted by several cancer cell types, including melanoma." (PMID 25939769, 2015). "We were unable to detect CSF1 expression in normal human fibroblasts or in melanoma cell lines that we have genotyped for P72 or R72 (G. Azzam, unpublished data)." (PMID 24019961, 2013). "In addition, melanoma delivers CSF1 and IL-34 to micro-glial cells, which activates micro-glial CSF1R and thereby expands a population of trophic/phagocytic micro-glial cells that remodel the extracellular matrix and maintain a non-inflammatory phenotype." (PMID 41463339, 2025). "Melanoma responds to this pro-inflammatory response by releasing suppressive mediators including CSF1, TGF-β, and CCL2, which reprogram micro-glial cells to become trophic, anti-inflammatory cells characterized by increased expression of Arg1, IL-10, and PD-L1." (PMID 41463339, 2025). "Furthermore, the cannabis extract treatment also depleted colony-stimulating factor 1 (CSF-1) secretion by melanoma cells." (PMID 39684447, 2024). "TAMs account for up to 30% of the melanoma tumor content and are polarized to an M2-like, immunosuppressive phenotype by melanoma cell-derived factors including but not limited to the B-cell lymphoma 2 protein, acidosis, colony-stimulating factor 1, CXCL12 and CCL2." (PMID 40838054, 2023). "Likewise, co-treatment of mice bearing BRAF V600E-driven melanoma with CSF-1R- and PD1-blocking antibodies increased efficacy when compared to single agent treatments, most likely due to the capacity of melanoma cell-derived CSF-1 to enhance TAM recruitment." (PMID 36175961, 2022). "In melanoma, for example, macrophage-associated markers including CSF1 were associated with nonresponsiveness to PD1 inhibition." (PMID 34063518, 2021). "Repolarization of macrophages from M2 to M1 was also achieved using self-assembled dual-inhibitor-loaded nanoparticles to target CSF-1 and Src homology 2 domain-containing phosphatase 2 pathways, which resulted in anti-tumor efficacy in mammary and melanoma pre-clinical mouse models." (PMID 33924237, 2021).